TLR4 (toll like receptor 4)
Diseases named in the same sentence as TLR4 in open-access papers (continued):
Sharing a sentence is not in itself a finding about the gene and the disease.
ovarian carcinoma (continued). "MyD88+ human ovarian carcinoma cells (SKOV3 and OVCAR3) and MyD88− ovarian carcinoma cell lines (A2780 and 3AO) were selected to investigate the TLR4 effects on apoptosis with Pac chemotherapy." (PMID 24527095, 2014). "Recent reports have identified CD44 as a potential marker for the identification of cancer stem cells in ovarian cancer, and confirmed the functionality of the TLR4-MyD88 pathway in only the CD44+ cell population." (PMID 22533866, 2012). "MyD88 positive EOC cells have a functioning TLR4/MyD88 pathway and are possibly indicative of an ovarian cancer stem cell that is highly resistant to pro-apoptotic signalling." (PMID 22533866, 2012). "The participation of TLR2 and TLR4 expressed on neutrophils in the interaction via HspA1A with ovarian cancer cells was also investigated." (PMID 22528050, 2012). "To demonstrate the role of TLR4/MyD88 signaling in ovarian epithelial cancers (OECs), we examined the expression of TLR4, MyD88 and nuclear factor- κB (NF-κB) in OECs." (PMID 22985132, 2012). "We found that fMLP and PMA significantly increased the expression of both TLR2 and TLR4 on ovarian cancer patients’ neutrophils." (PMID 22528050, 2012). "et a1 found that activation of TLR4 signaling promotes the growth and chemoresistance of epithelial ovarian cancer cells." (PMID 20618976, 2010). "Paclitaxel’s impact on TAM polarization through TLR4 could be leveraged to strengthen antitumor immunity in ovarian cancer, offering a promising strategy for combination cancer therapies." (PMID 40330466, 2025). "TLR4 expression was markedly elevated in ovarian cancer tissues compared to normal tissues." (PMID 40999508, 2025). "In ovarian cancer, high expression of TLR4 could activate NF-κB signaling pathway, thus up-regulated ALKBH5 to influence the m6A methylation of NANOG, which further promoted carcinogenesis in ovarian cancer." (PMID 38637813, 2024). "Meanwhile, the ability of the HIF-1α expression plasmid to enhance the TLR4 expression and the ability of HIF-1α shRNA to inhibit the TLR4 expression provided additional evidence to sustain the role of HIF-1α on regulating the expression of TLR4 in ovarian cancer cells." (PMID 35464826, 2022). "Our findings may provide more promising therapeutic strategies for epithelial ovarian cancer based on the inhibition of the TLR4/NF-κB/HIF-1 loop." (PMID 35464826, 2022). "Moreover, hypoxia treatment augmented the responsiveness of ovarian cancer cells to LPS, including the TLR4 expression level and the downstream NF-κB and HIF-1α activities." (PMID 35464826, 2022). "Past studies have demonstrated that the activation of TLR4 signaling generates proinflammatory cytokines and antiapoptotic proteins, which in turn contributes to the growth, metastasis, and chemoresistance in ovarian cancer." (PMID 35464826, 2022). "In addition, MyD88-positive EOC cells have a functioning TLR4/MyD88 pathway and are possibly indicative of an ovarian cancer stem cell that is highly resistant to proapoptotic signaling." (PMID 35464826, 2022). "In addition, decreased TLR4 expression has been observed in ovarian carcinoma after treating with NF-κB inhibitor." (PMID 31318878, 2019). "Furthermore these miRs target WNT signaling, AKT/mTOR signaling and TLR-4/MyD88 to regulate ovarian cancer progression and resistance." (PMID 31608277, 2019). "The TLR4–NF-κB pathway has been intensively studied in several cancers such as laryngeal carcinoma and ovarian carcinoma as prognostic markers and inhibiting of the pathway might serve as a potential treatment of the cancers." (PMID 31318878, 2019). "In human epithelial ovarian cancer tested on tissue samples of 500 patients by immunohistochemistry, it was shown that expression of TLR4 and MyD88 predicts poorer overall patient survival apparently due to favoring inflammatory microenvironment at the site of tumor growth." (PMID 30976817, 2019).
ovarian carcinoma (continued). "Additionally, we assessed the clinical applicability of PAUF and TLR4 expression as a prognostic and predictive biomarker in ovarian cancers." (PMID 30111860, 2018). "PTX could induce NF-κB and cJUN activation to promote IL-6, IL-8, VEGF and MCP-1 productions via a TLR4/MyD88-dependent pathway and resisted drug-induced apoptosis in ovarian cancer." (PMID 29486738, 2018). "We examined the link between PAUF and TLR4 in ovarian cancer cell lines." (PMID 30111860, 2018). "Therefore, the assessment of PAUF and TLR4 expression can potentially serve as a new prognostic indicator predicting survival time, and can be helpful in management of patients with ovarian cancer." (PMID 30111860, 2018). "Thus, the metastatic ability of ovarian cancer cells is promoted by TLR4 activation via the up-regulation of OPN expression." (PMID 29228698, 2017). "Thus, up-regulation of OPN expression following TLR4 activation was an important factor that facilitated the malignant metastasis of ovarian cancer cells." (PMID 29228698, 2017). "In this study, we found a high expression level of TLR4 in the human ovarian cancer cell line (HO-8910PM), suggesting that TLR4 elicited essential biological functions and could be used as a potential target for the immune treatment of cancer." (PMID 29228698, 2017). "TLR4 negatively regulates Pac chemotherapy, particularly in terms of cell proliferation, and TLR4 may be a novel treatment target in Pac-resistant ovarian cancer." (PMID 24527095, 2014). "Characterisation of TLR4 & MyD88 expression in ovarian cancer." (PMID 24977712, 2014). "Thus, the silencing of TLR4 generated a more chemosensitive phenotype in the SKOV-3 ovarian cancer cells." (PMID 24977712, 2014). "In the present study, the relevance of TLR4 SNPs, Asp299Gly (rs4986790) and Thr399Ile (rs4986791) are investigated in 105 ovarian cancer patients retrospectively with an extended follow-up and complete representative adjuvant therapy (chemotherapy with or without surgical treatment)." (PMID 24959291, 2014). "Importantly, TLR4 expression in ovarian cancer cells has been shown to exert protumor activities and to hamper the efficacy of paclitaxel therapy." (PMID 22530148, 2012). "Besides, it has been further unveiled that LINC00886 impacts the malignant progression and immune evasion of ovarian cancer by modulating miR-423-5p and the downstream TLR4 signaling pathway, offering a fresh perspective for therapeutic interventions in ovarian cancer." (PMID 40999508, 2025). "Similarly, TLR4 appears to have a prognostic role in ovarian cancer progression." (PMID 40871563, 2025). "Similarly, TLR-4 appears to have a prognostic role in ovarian cancer progression as well." (PMID 38339334, 2024). "The aim of this study, therefore, was to assess whether there was any molecular link between MAD2, TLR4 and MyD88 in ovarian cancer and to further explore the mechanisms each of these biomarkers utilise, in order to render ovarian cancer cells resistant to paclitaxel therapy." (PMID 33370338, 2020). "Thus, we hypothesized that the PAUF/TLR4 signaling pathway may play a role in the development of ovarian cancer and potentially a novel target for treatment." (PMID 30111860, 2018). "Moreover, TLR4 has been involved in its impact on PTX resistance causing the increase of pro-inflammatory cytokines and their receptors to favor cancer aggressiveness and chemoresistance in ovarian cancers." (PMID 29486738, 2018). "Therefore, the effect of TLR4 on the proliferation and metastasis of ovarian cancer cells was studied and it was found that the proliferation, anchorage-independent growth, migration and invasion abilities are significantly increased after stimulation with LPS." (PMID 29228698, 2017).
ovarian carcinoma (continued). "MyD88 positive EOCs have a functioning TLR4/MyD88 pathway and may represent an ovarian cancer stem cell (CSC) that is highly resistant to pro-apoptotic signaling and which can recruit leukocytes to actively promote a pro-inflammatory, pro-proliferative microenvironment." (PMID 24977712, 2014). "In breast, prostate, and ovarian cancers, studies using their corresponding cancer cell lines or primary cancer cells from patients all provided evidence to support that LPS could promote production of proinflammatory cytokines from cancer cells by signaling through TLR4 and MyD88." (PMID 36765715, 2023). "The physical presence of certain vaginal microbes, as Lactobacillus lactis, can modulate the responsiveness of TLR4 though modulating the expression of miR-21 and miR-200b and, hence, decrease responsiveness of CAOV-4 ovarian cancer cells to LPS." (PMID 33794773, 2021). "In order to discern a possible relationship between MAD2 and TLR4-MyD88 signalling, transfection experiments were performed initially in both A2780 (MyD88 null) and SKOV-3 (MyD88 positive) ovarian cancer cells." (PMID 33370338, 2020). "The molecular link between TLR4-MyD88 signalling and MAD2 identified in this study has potentially important implications for the development of new treatment strategies for ovarian cancer patients." (PMID 33370338, 2020). "These initial transfection experiments and the in-silico analysis supported the idea that TLR4-MyD88 signalling and MAD2 acted as independent biomarkers in ovarian cancer." (PMID 33370338, 2020). "It is suggested that the expression of TLRs, TLR4, TLR9 and TLR10 was significantly reduced in the local macrophage‐infiltrating microenvironment of ovarian cancers." (PMID 32329191, 2020). "The expression levels of TLR4, TLR9 and TLR10 were significantly enhanced in the local macrophage‐infiltrating microenvironment of ovarian cancer." (PMID 32329191, 2020). "In the ovarian cancer cells co‐cultured with M2 macrophages, the expression of ALKBH5 and TLR4 increased." (PMID 32329191, 2020). "It provides new insights for the mechanisms of tumor development and metastasis, and suggests targeting TLR4 and OPN as an intervention in the ovarian cancer treatment." (PMID 29228698, 2017). "Taken together, our study investigates the mechanisms of tumorigenesis, development, and metastasis, and provides evidence for the combined targeting of TLR4 and OPN in the treatment of ovarian cancer." (PMID 29228698, 2017). "In the current study, the human ovarian cancer cell line, HO-8910PM, was investigated to examine the expression levels of TLR4 and OPN in ovarian cancer cells." (PMID 29228698, 2017). "The current study investigated the role of TLR4 and OPN in tumor proliferation and metastasis, and the potential effect of TLR4 signaling on OPN using the human ovarian cancer cell line HO-8910PM." (PMID 29228698, 2017). "Specifically for ovarian cancer, Zhou and colleagues have shown show that TLR2, TLR3, TLR4, and TLR5 are highly expressed on the normal ovarian epithelium, as well as on neoplastic ovarian epithelial cells." (PMID 22530148, 2012). "In the second experiment, we observed a weak positive correlation between TLR4 and PAUF mRNA expression using the PC cell data from the CCLE database (n = 52, r = 0.363, p = 0.008), a similar correlation was reported in ovarian cancer patients at the protein level (n = 182, r = 0.256, p = 0.001)." (PMID 36232715, 2022). "In ovarian cancer patients, a statistically significant but weak correlation between the protein expression of PAUF and TLR4 was reported, how the two molecules are related and whether TLR4 acts as a PAUF receptor have not yet been studied." (PMID 36232715, 2022). "Reportedly, the toll-like receptor 4 (TLR4)/nuclear factor kappa B (NF-κB) pathway and hypoxia-inducible factor-1α (HIF-1α) are activated and closely related to the chemoresistance and poor prognosis of epithelial ovarian cancer (EOC)." (PMID 35464826, 2022).
ovarian carcinoma (continued). "However, when ovarian cancer cells were co-cultured with M2 macrophages, the expressions of ALKBH5 and TLR4 were both increased." (PMID 33611339, 2021). "Besides, it has been revealed that the inhibition of TLR4 using small molecule inhibitor TAK‐242 suppressed NF‐кB–related anti‐apoptosis genes BCL‐xL, BCL‐2 and survivin in breast and ovarian cancer cells and led to increased apoptosis." (PMID 33336901, 2021). "Since PAUF is an endogenous ligand for TLR4, we investigated whether PAUF could induce cancer cell activation and cancer proliferation via TLR4 using PAUF and TLR4 expressing ovarian cancer cell lines (A2780 and SKOV3)." (PMID 30111860, 2018). "Our earlier report also demonstrates that in absence of TLR4/MyD88 signalling, ovarian cancer chemoresistance is maintained by NF-κB transcriptional activation under cisplatin treatment." (PMID 29169370, 2017). "Our study provides a theoretical basis for the mechanisms of tumorigenesis, development and metastasis, and TLR4 and OPN may serve as potential combined targets for future therapy of ovarian cancer." (PMID 29228698, 2017). "Currently, our study demonstrates for the first time that activation of ovarian cancer patients’ neutrophils by ovarian cancer cells is dependent on the interaction of HspA1A originating from ovarian cancer cells, with TLR2 and TLR4 expressed on the surface of neutrophils." (PMID 22528050, 2012). "Unfortunately, by inducing immunosuppressive cytokines, apoptosis resistance, and EMT, the TLR4 signaling pathway can promote cancer cells’ immune escape in several cancer types (including lung, pancreas, and ovarian cancers, HNSCC) as well as resistance to therapy (paclitaxel in ovarian cancer)." (PMID 33718169, 2021). "Most interestingly when MAD2 levels were suppressed using siRNA, both A2780 and SKOV-3 cells exhibited a significant 3-fold increase in TLR4 gene expression, demonstrating a previously never-before shown link between TLR4 and MAD2 in ovarian cancer." (PMID 33370338, 2020).
lupus (86 papers, 2010 to 2026). "A meta-analysis for the association of TLR4 polymorphism with the susceptibility to develop systemic lupus erythematosus was done in 2016." (PMID 34468896, 2021). "As previous research showed, TLR4-deficient lupus prone mice demonstrated a more global decrease in immune responses, cytokine production, autoantibody production, and attenuation in renal damage." (PMID 29194423, 2017). "Further testing of disease outcome through TLR4 knockout should be done in additional strains of lupus-prone mice to determine the role of TLR4 deficiency in lupus." (PMID 26648937, 2015). "Pristane-induced lupus was studied in C57BL/6 TLR4 deficient mice and both autoantibodies and nephritis was found to be ameliorated compared to controls." (PMID 24086313, 2013). "Additionally, there is a dramatic decrease in glomerular IgG deposition and mesangial cell proliferation with reduced autoantibody titers in TLR-2- or TLR-4-deficient MRL lymphoproliferation strain (MRL/lpr) lupus mice." (PMID 35897790, 2022). "We next investigated whether the hyper-responsiveness of DKO BMDCs to TLR4 stimulation would extend to IFNβ, another key cytokine produced by DCs, which together with IL-10, has been implicated in lupus pathogenesis." (PMID 26544714, 2015). "Specifically, HMCs were used as the subjects, and the lupus environment was induced using the TLR4 agonist LPS to construct a model of kidney damage in vitro." (PMID 41466499, 2026). "NEU1 activity promotes IL-6 secretion from lupus-prone MRL/lpr primary mouse mesangial cells (MCs) in response to an IgG mimic, and to circulating lupus factors through the TLR4-MAPK p38 or ERK signaling pathway." (PMID 39194692, 2024). "Anti-double-stranded DNA antibodies, the hallmark antibody of systemic lupus erythematosus (SLE), have been found to bind to TLR4, which in turn activates NLRP3 inflammasome." (PMID 37386410, 2023). "The contribution of membrane-bound TLR4 to the development of autoimmunity has been consistently demonstrated in transgenic lupus mouse models." (PMID 37700342, 2023). "LPS interacts with its receptor, toll-like receptor 4 (TLR4) whose activation has been shown to exacerbate lupus." (PMID 35833129, 2022). "In in vivo studies, we investigated the effect of the ACK1 inhibitor AIM-100 on TLR4 agonist LPS-mediated endotoxic shock model mice and lupus-prone model mice." (PMID 35669783, 2022). "We believe that it will be more meaningful for researchers to use ACK1 knockout mice to further study the regulatory function of ACK1 on TLR4 agonist LPS-mediated endotoxic shock model mice and lupus-prone model mice." (PMID 35669783, 2022). "The attenuation of NETs using Syk inhibitor, possibly through reduction of the downstream signaling of TLR-4 and Fc gamma receptors, was proposed as an interesting strategy for the treatment in lupus." (PMID 34248948, 2021). "Studies have unveiled the promoted levels of TNF-α and C-C Motif Chemokine Ligand 5 (CCL5) mRNA provoked by TLR4 and TLR7 in spleen macrophages of lupus-susceptible mice." (PMID 32760274, 2020). "Mice spontaneously develop lupus when TLR4 responsiveness is increased, whereas the exacerbated disease phenotype can be significantly ameliorated when the commensal gut flora is removed by antibiotic treatment." (PMID 28588585, 2017). "Second, in a lupus mouse model, the deletion of TLR4 or TLR2 (to a lesser extent) decreases the levels of autoantibodies, and subsequently ameliorates the disease symptoms." (PMID 28769820, 2017). "Conversely, inhibition of TLR4 results in reduced autoantibody production and lowered renal glomerular IgG deposits in lupus-prone mice." (PMID 28588585, 2017). "Over-expression of TLR4 in mice leads to the production of anti-dsDNA IgG and immune complex-mediated glomerulonephritis, suggesting that TLR4 signaling plays a role in lupus progression." (PMID 27232337, 2016).